JAM3 (junctional adhesion molecule 3)
Description:
Junctional adhesion protein that mediates heterotypic cell-cell interactions with its cognate receptor JAM2 to regulate different cellular processes. Plays a role in homing and mobilization of hematopoietic stem and progenitor cells within the bone marrow. At the surface of bone marrow stromal cells, it contributes to the retention of the hematopoietic stem and progenitor cells expressing JAM3. Plays a central role in leukocytes extravasation by facilitating transmigration through the endothelium (By similarity). Plays a role in spermatogenesis where JAM2 and JAM3, which are respectively expressed by Sertoli and germ cells, mediate an interaction between both cell types and play an essential role in the anchorage of germ cells onto Sertoli cells and the assembly of cell polarity complexes during spermatid differentiation (By similarity). Also functions as a counter-receptor for ITGAM, mediating leukocyte-platelet interactions and is involved in the regulation of transepithelial migration of polymorphonuclear neutrophils (PMN). Plays a role in angiogenesis. Plays a role in the regulation of cell migration (Probable). During myogenesis, it is involved in myocyte fusion (By similarity). [Soluble form of JAM-C]: Promotes chemotaxis of vascular endothelial cells and stimulates angiogenesis.
Synonyms: JAM-C; JAM-3; JAMC; JAM-2
Tractability: Antibody: UniProt places it where antibodies can reach, with high confidence; its Gene Ontology location is reachable by antibodies, with high confidence; UniProt predicts a signal peptide or a membrane-spanning region. PROTAC: ubiquitination databases record sites on it; its protein half-life has been measured.
Gene: Protein-coding gene on chromosome 11 (134,068,998 to 134,152,001, forward strand). Ensembl gene ENSG00000166086.
Subcellular location: Cell membrane; Cell junction; Cell junction, desmosome; Cell junction, tight junction; Secreted (Soluble form of JAM-C)
Subcellular location (Human Protein Atlas): Golgi apparatus; Predicted to be secreted
Pathways (Reactome):
Extracellular matrix organization: Integrin cell surface interactions
Hemostasis: Cell surface interactions at the vascular wall
Gene Ontology:
Molecular function: cell-cell adhesion mediator activity; identical protein binding; integrin binding; protein binding; protein heterodimerization activity; protein homodimerization activity
Biological process: adherens junction assembly; angiogenesis; apical protein localization; cell-cell adhesion; granulocyte migration; hematopoietic stem cell migration to bone marrow; heterotypic cell-cell adhesion; negative regulation of cell adhesion mediated by integrin; negative regulation of integrin activation; positive regulation of membrane permeability; positive regulation of monocyte extravasation; protein localization to cell junction; protein localization to cell surface; regulation of neutrophil chemotaxis; cell migration; maintenance of blood-brain barrier; cell adhesion; leukocyte migration; system development
Cellular component: anchoring junction; bicellular tight junction; cell-cell contact zone; cell-cell junction; desmosome; extracellular region; filamentous actin; microvillus; plasma membrane; protein complex involved in cell adhesion; tight junction; paranodal junction; Schmidt-Lanterman incisure
Genetic constraint (gnomAD): Loss-of-function variants: 25 observed, 34.8 expected, observed/expected ratio (o/e) 0.72, 90% interval 0.52 to 1. The upper end of that interval is the gene's LOEUF score, 1, which puts it in group 4 of 6, group 1 being the genes least tolerant of losing a copy. Missense variants: 420 observed, 383.63 expected, observed/expected ratio (o/e) 1.09, 90% interval 1.01 to 1.19. Synonymous variants: 179 observed, 150.23 expected, observed/expected ratio (o/e) 1.19, 90% interval 1.05 to 1.35.
Homologues: Orthologues: chimpanzee JAM3 (100% identical), macaque JAM3 (95% identical), dog JAM3 (90% identical), rabbit JAM3 (89% identical), guinea pig JAM3 (88% identical), mouse Jam3 (86% identical), pig JAM3 (84% identical), rat Jam3 (80% identical), tropical clawed frog jam3 (63% identical), zebrafish jam3b (56% identical), zebrafish jam3a (44% identical). Paralogues in human: JAM2 (34% identical), F11R (31% identical), VSIG2 (22% identical), CXADR (21% identical), VSIG1 (21% identical), IGSF11 (20% identical), ESAM (20% identical), VSIG8 (20% identical), CLMP (19% identical), MXRA8 (19% identical), GPA33 (18% identical), MUC15 (14% identical), and 2 more.
Diseases named in the same sentence as JAM3 in open-access papers:
JAM3 is named in the same sentence as 121 diseases in open-access papers, as found by Europe PMC text mining. Sharing a sentence is not in itself a finding about the gene and the disease. The quoted sentences say what the papers report.
cervical cancer (11 papers, 2015 to 2025). A primary or metastatic malignant neoplasm involving the cervix. "Because the JAM3 methylation marker we identified is specific to cervical cancer and discriminative among all diagnostic groups, the role of this gene in carcinogenesis is of interest." (PMID 26517242, 2015). "Aberrant methylation of JAM3 has also been associated with cervical cancer." (PMID 29137428, 2017). "In cervical cancer, JAM3 overexpression activated the HIF-1α/VEGFA pathway, promoting cell migration and invasion, whereas silencing of JAM3 inhibited these processes." (PMID 40507913, 2025). "In conclusion, our results suggested that JAM3 promotes cervical cancer cell migration and invasion by activating the HIF-1α/VEGFA pathway." (PMID 38760803, 2024). "We found that JAM3 was highly expressed in cervical cancer patients with lymph node metastasis and that high expression of JAM3 promoted cervical cancer cell metastasis both in vitro and in vivo." (PMID 38760803, 2024). "The methylation status of JAM3 has been proposed as a marker for cervical cancer." (PMID 35013102, 2022). "Moreover, silencing JAM3 suppressed cervical cancer cell migration and invasion in vitro." (PMID 38760803, 2024). "JAM3 may be a promising biomarker and effective therapeutic target for cervical cancer." (PMID 38760803, 2024). "The host EPB41L3 and JAM3 gene methylation assay in cervical cytology had favorable diagnostic accuracy for CIN2+ and was highly specific for residual CIN2+ lesions The methylation assay is a promising triage tool in hrHPV+ women, or even an independent tool for cervical cancer screening." (PMID 37671063, 2023). "Overexpression of E6 / E7, p16 /ki-67, miR-9, SCC-Ag, M-CSF, VEGF proteins, or JAM3, SOX1, and L1 genes following infection with HPV can be detected based on their elevated levels in plasma, serum, Cervical scraping, or tissue as predictors of increased risk of cervical cancer progression." (PMID 33292364, 2020). "Junctional adhesion molecule 3 (JAM3) is an important member of the TJ tight junction (TJ) family, and its biological function in cervical cancer needs to be further clarified." (PMID 38760803, 2024). "Despite rapid improvements in DNA methylation tools for cervical cancer screening, few robust, exploratory studies have been performed using the combination of two host genes, EPB41L3 and JAM3, newly developed assays." (PMID 32576279, 2020). "Cervical cancer and normal cervix tissue was used to select the top 5 discriminating loci among 27 loci in 4 genes (CCNA1, CADM1, DAPK1, JAM3), and one locus of JAM3 (region M4) was identified and confirmed with 267 and 224 cervical scrapings from 2 independent colposcopy referral studies." (PMID 26517242, 2015). "Various host cell methylated genes such as SOX1, PAX1, JAM3, EPB41L3, CADM1, and MAL have been investigated for predicting cervical lesions, with PAX1 gene methylation showing the most significant correlation with the progression of cervical intraepithelial neoplasia and cervical cancer occurrence." (PMID 39155349, 2024).
colorectal cancer (11 papers, 2022 to 2025). A primary or metastatic malignant neoplasm that affects the colon or rectum. "JAM3 serves as a tumor suppressor in colorectal cancer, and methylation of JAM3 is associated with cervical intraepithelial neoplasia malignant transformation." (PMID 36461092, 2022). "JAM3 is a junctional adhesion molecule that is associated with several cancers and is thought to function as a tumor suppressor in colorectal cancer." (PMID 35013102, 2022). "In the field of cancer research, the expression of JAM3 is silenced by the gene methylation in colorectal cancer and esophageal cancer, showing a close relationship between gene functions of JAM3 and its relative methylation level." (PMID 38400838, 2024). "JAM3 was downregulated in primary colorectal cancer tissues and this was thought to be influenced by methylation." (PMID 35013102, 2022). "JAM3, an adhesion and transmigration regulatory element, has been identified as a tumor suppressor gene through DNA methylation in colorectal cancer, but it has also been described to inhibit apoptosis and induce cell migration in renal carcinoma." (PMID 35768842, 2022). "JAM3 exhibits frequent hypermethylation and concomitant downregulation in colorectal cancer." (PMID 39781359, 2025). "JAM3 functions as a novel tumor suppressor and is inactivated by DNA methylation in colorectal cancer, and the role in leukemia is unknown." (PMID 38322112, 2024). "Junctional adhesion molecular 3 has also been shown to be frequently methylated and downregulated in colorectal cancer tissues, cell lines and plasma samples, while restoration of JAM3 has been found to repress CRC cell viability, colony formation and migration." (PMID 38124399, 2024). "JAM3, an adhesion and transmigration regulatory element, is a novel tumor suppressor in colorectal cancer, and siRNA-mediated depletion of JAM3 increased cell invasion and migration." (PMID 36855119, 2023). "Furthermore, we found that several genes coding for junctional adhesion molecules (JAM) (JAM2 and JAM3) have H3K4me3 peaks in normal colon cells but not in colorectal cancer cells." (PMID 40141189, 2025).
melanoma (10 papers, 2012 to 2024). A malignant, usually aggressive tumor composed of atypical, neoplastic melanocytes. "The mRNA levels of JAM3 are higher in metastatic malignant melanomas and its expression is correlated with invasive properties and metastatic potential either in fibrosarcoma or melanoma and also in bladder cancer cell lines." (PMID 39202425, 2024). "JAM3 promoted hematogenous lung metastasis in melanoma and in an experimental metastatic model in vivo." (PMID 26517242, 2015). "JAM3 promotes cell migration and invasion in melanoma and glioma." (PMID 32979257, 2020).
Hydrocephalus (8 papers, 2012 to 2024). Hydrocephalus is an active distension of the ventricular system of the brain resulting from inadequate passage of CSF from its point of production within the cerebral ventricles to its point of absorption into the systemic circulation. "JAM3 mutations or deficiencies in humans and mice also result in hemorrhages in the brain and hydrocephalus, suggesting that JAM3 is associated with the regulation of BBB integrity." (PMID 36469195, 2023). "Moreover, mice deficient for JAM-3 develop a severe hydrocephalus, suggesting a role of this tight junction complex protein in brain development and cerebrospinal fluid homeostasis." (PMID 38338705, 2024). "In mice, loss of the junctional adhesion molecule C (Jam3) also causes hydrocephalus." (PMID 28500065, 2017). "JAM3-deficient mice show megaesophagus, failure to thrive (FTT), jitteriness, multilobar pneumonia, brain hemorrhages, and communicating hydrocephalus." (PMID 37780041, 2023). "Similar as in Jam3‐deficient mice, the endothelium was not responsible for hydrocephalus development in Mpdz−/− mice." (PMID 28500065, 2017). "Furthermore, a communicating hydrocephalus has occurred in mice knockout models for JAM3, suggesting that JAM3 has an additional function in permeability and CSF homeostasis; thus, the CNS phenotype is variable due to several interactions and functions of JAM3." (PMID 37780041, 2023).
Sepsis (8 papers, 2020 to 2025). Sepsis is defined as life-threatening organ dysfunction caused by a dysregulated host response to infection. "SMAD4 has been linked to the regulation of intercellular tight junction by increasing expression of junctional adhesion molecule (JAM-3) during sepsis." (PMID 34646379, 2021).
congenital cataracts (6 papers, 2015 to 2025). "One example is the syndrome of hemorrhagic destruction of the brain, subependymal calcification, and congenital cataracts (HDBSCC) caused by mutations in JAM3 (which encodes junctional adhesion molecule 3)." (PMID 40937018, 2025). "In particular, JAM3 mutations are known to cause congenital cataracts and hemorrhagic destruction of the brain." (PMID 37847489, 2024). "We suggest including JAM3 in the gene list known to cause prenatal/congenital cataracts and hearing loss." (PMID 37780041, 2023). "We suggest including JAM3 in the gene list known to cause congenital cataracts, brain hemorrhages, and hearing loss." (PMID 37780041, 2023). "Homozygous mutations in JAM3 cause hemorrhagic destruction of the brain, subependymal calcification, and congenital cataracts (HDBSCC, OMIM #613730)." (PMID 26401656, 2015). "JAM3 screening should be requested in prenatal diagnostic screening for congenital cataracts." (PMID 37847489, 2024).
leukemia (6 papers, 2020 to 2024). A malignant (clonal) hematologic disorder, involving hematopoietic stem cells and characterized by the presence of primitive or atypical myeloid or lymphoid cells in the bone marrow and the blood. "In leukemia, JAM3 maintains leukemia-initiating cell function through the LRP5/AKT/β-catenin/CCND1 signaling pathway and is associated with poor prognosis in leukemia." (PMID 38400838, 2024). "By activating Wnt signaling, JAM3 plays an important role in the maintenance of leukemia-initiating cells stemness." (PMID 36461092, 2022). "JAM3 is highly enriched in leukemia-initiating cells and play an important role in the maintenance of leukemia-initiating cell stemness through LRP5/PDK1/AKT/GSK3β/β-catenin/CCND1 signaling pathways." (PMID 32979257, 2020). "Leukaemia‐initiating cells, which present high JAM3 expression, are important for the initiation, development, and relapse of leukaemia, while knockdown of JAM3 has been shown to dramatically decrease the proliferation of leukaemia cell lines and primary leukaemia‐initiating cells." (PMID 38124399, 2024). "JAM3 have been reported to be involved in Wnt signaling in leukemia initiation." (PMID 36461092, 2022). "Knockdown of JAM3 leads to a dramatic decrease in leukemia-initiating cell proliferation." (PMID 32979257, 2020).
cervical intraepithelial neoplasia (5 papers, 2022 to 2026). "The effectiveness of PAX1/JAM3 methylation in detecting high‐grade cervical intraepithelial neoplasia (CIN) was compared to traditional screening methods." (PMID 41239544, 2026). "In a previous training set with a case-controlled design, cutoff values for host EPB41L3 and JAM3 gene methylation were obtained for the detection of cervical intraepithelial neoplasia (CIN) 2 or more severe lesions (CIN2+)." (PMID 37671063, 2023).
renal carcinoma (5 papers, 2022 to 2024). A carcinoma arising from the epithelium of the renal parenchyma or the renal pelvis. "The exogenous knockdown of JAM3 has been shown to inhibit renal carcinoma cell migration and promote renal carcinoma cell apoptosis via regulation of E‐cadherin, N‐cadherin, integrin β1 and MMP2 expression." (PMID 38124399, 2024). "Similarly, JAM3 was found highly expressed in renal carcinoma cells, inhibited tumor cell apoptosis, and promoted cell migration by upregulating levels of N-Cadherin, integrin β1, and MMP-2." (PMID 38400838, 2024). "Additionally, JAM3 suppresses apoptosis and promotes migration in renal carcinoma." (PMID 35013102, 2022).
cataract (4 papers, 2012 to 2025). Partial or complete opacity of the crystalline lens of one or both eyes that decreases visual acuity and eventually results in blindness. "Several individuals from a single large family with autosomal recessive JAM3 mutations presented all bilateral cataracts and some of them had hepatomegaly and thrombocytopenia." (PMID 28460636, 2017). "This triad of intracerebral hemorrhages, calcifications, and cataracts is pathognomonic for JAM3-related disease." (PMID 40937018, 2025). "It is challenging to confirm the relationship between the novel phenotypes (auditory neuropathy, FTT, and early onset cataracts) described here to the HDBSCC syndrome and the JAM3 genetic variant." (PMID 37780041, 2023). "In an Italian patient, cataracts were also suspected prenatally, suggesting the role of JAM3 in early genesis of the lenses." (PMID 37780041, 2023). "Pathogenic variants of the junctional adhesion molecule 3 (JAM3/JAM-C; OMIM#606871) is the cause of the rare recessive disorder called hemorrhagic destruction of the brain, subependymal calcification, and cataracts (HDBSCC, OMIM#613730) disease." (PMID 37780041, 2023). "Considering the unique features of cataracts and brain hemorrhages and consanguinity, Sanger sequencing of JAM3(NM_032801) was performed according to established protocols." (PMID 37780041, 2023).
esophageal cancer (4 papers, 2022 to 2024). A primary or metastatic malignant neoplasm involving the esophagus. "The methylation level of JAM3 is identified as an independent risk factor in esophageal cancer by activating the Wingless-related integration site (Wnt) signaling pathway, showing the tumor suppression function of JAM3." (PMID 38400838, 2024). "Junctional adhesion molecular 3 shows differential expression in oesophageal cancer cell lines, with an inverse association observed between JAM3 RNA expression and methylation." (PMID 38124399, 2024). "The methylation status is correlated with loss of/reduced expression of JAM3 in esophageal cancer cells." (PMID 36461092, 2022). "Methylation within the promoter region of JAM3 has been observed by certain scholars in 26.5% (13 out of 49) of precancerous lesions associated with esophageal carcinoma and in 51.1% (388 out of 760) of primary esophageal carcinomas, thereby modulating the expression of JAM3." (PMID 39184862, 2024). "In esophageal carcinoma, JAM3 induces G1/S arrest, inhibits the Wnt pathway to suppress cell proliferation, and promotes apoptosis." (PMID 39184862, 2024). "The methylation of JAM3 is an independent prognostic factor of overall survival for oesophageal cancer." (PMID 38124399, 2024). "JAM3 is frequently methylated in human esophageal cancer, and the expression of JAM3 is regulated by promoter region methylation." (PMID 36461092, 2022). "The epigenetic regulation and the mechanism of JAM3 remain to be elucidated in human esophageal cancer (EC)." (PMID 36461092, 2022). "The expression of JAM3 is examined by immunohistochemistry (IHC) in 52 cases of available matched esophageal cancer and adjacent tissue paraffin samples." (PMID 36461092, 2022). "Western blot was employed to determine whether JAM3 is involved in Wnt signaling pathway in human esophageal cancer." (PMID 36461092, 2022). "The role and the mechanism of JAM3 in esophageal cancer development remains to be elucidated." (PMID 36461092, 2022). "The number of migratory cells was significantly reduced after restoration of JAM3 expression in KYSE30 and KYSE410 cells and increased significantly after knockdown of JAM3 expression in YES2 and KYSE450 cells, suggesting that JAM3 suppresses esophageal cancer cell migration." (PMID 36461092, 2022). "The expression of JAM3 was detected by semiquantitative RT-PCR in human esophageal cancer cells." (PMID 36461092, 2022).